IL18 (interleukin 18)
Diseases named in the same sentence as IL18 in open-access papers (continued):
Sharing a sentence is not in itself a finding about the gene and the disease.
tumor (continued). "One reason for this correlation is that in patients with high NLR, tumor growth may be supported by neutrophil-derived cytokines such as vascular endothelial growth factor, interleukin-18, and matrix metalloproteinases." (PMID 36675747, 2022). "Summarizing the obtained data, it would be worth considering the use of DC-based vaccines in therapy, consisting of DC/IL-18 + IL-12/TAg cells, which are characterized by an increased ability to infiltrate tumor tissue, and DC/TAg, which migrated most effectively to the lymph nodes." (PMID 35372586, 2022). "Indeed, ablation of IL-18 signaling in IL-18−/− and Il18r1−/− mice also resulted in higher tumor burden in the liver, and consistently recombinant IL-18 was able to reduce metastasis growth in Ice−/– mice." (PMID 35887206, 2022). "Besides IL-12, IL-18 also enhances Th1 function, and IL-18-expressing CD19-CAR-T cells exhibit augmented activity in mice bearing ALL tumor." (PMID 36248810, 2022). "Conversely, IL-18 also comes to terms with tumor immune responses to support cancer evasion." (PMID 36119049, 2022). "Furthermore, pyroptotic cells release pro-inflammatory cytokines such as IL-1β and IL-18 along with various DAMPs that prime an auxiliary anti-tumor immune response." (PMID 36376979, 2022). "The application of dendritic cells producing IL-12 only resulted in a statistically significant TGI of MC38 tumors amounted to 65.77%, whereas the use in the therapy of dendritic cells producing IL-12 and IL-18 simultaneously resulted in increase in tumor growth inhibition to 70.25%." (PMID 35372586, 2022). "Macrophages may internalize and secrete TNF- α, NO, IFN-γ, IL-2, IL-6, IL-8, IL-12 and IL-18, so as to play an anti-inflammatory and even anti-tumor role." (PMID 35299759, 2022). "Furthermore, not all the transcripts associated with the inflammasome complex were enriched in the tumor, such as IL18, AIM2, PYCARD, and GSDMD." (PMID 36439171, 2022). "In a similar way, it was shown that CAR-T cells producing IL-18 promote antitumor immune responses by modifying the tumor environment notably by increasing the density of M1 macrophages and NK cells and by decreasing Treg infiltration, CD103+ suppressive DCs and M2 macrophages frequency." (PMID 35211124, 2022). "It should be emphasized that DC/IL-18 + IL-12/TAg cells showed the greatest ability to infiltrate tumor tissue already on the 3rd day after administration, and then, their number during the following days of observation diminished more slowly than in other groups." (PMID 35372586, 2022). "Interestingly, the absence of IFNγ completely abolished the high antitumor capacity induced by IL-12+IL-18 expression, indicating an important role for these cytokines in early tumor growth control." (PMID 36330506, 2022). "IL-18 also promotes tumor progression by inducing an immunosuppressive microenvironment." (PMID 35739593, 2022). "Moreover, tumor-derived IL-18BP is an immune checkpoint molecule that inhibits IL-18 mediated anti-tumor activity in mouse and human tumors." (PMID 36032110, 2022). "On the one hand, pyroptosis alters the tumor microenvironment and inhibits tumor growth by releasing inflammatory factors such as IL-1β and IL-18; on the other hand, pyroptosis reduces the immune responses of the body to tumor cells and accelerates the growth rate of different cancers." (PMID 36142404, 2022). "The anti-tumor effect of IL-18 blocks tumors development as well as inhibits angiogenesis and may induce epithelial cell recovery." (PMID 36389791, 2022). "To test this hypothesis, we first evaluated tumor growth and size after systemic expression of IL-12+IL-18 in B16-bearing WT or IFNγKO mice (GKO)." (PMID 36330506, 2022). "Analysis of flash-frozen whole-tumour lysate revealed substantial levels of IL-1α, IL-1β and IL-18." (PMID 35545675, 2022). "In contrast, studies have also demonstrated a dual function of IL-18 in tumor progression." (PMID 36289606, 2022).
tumor (continued). "Moreover, the ratio of Th1/2 cytokines as well as the levels of IL-12, IL-18, IFNγ and GM-CSF was markedly elevated in RdB/IL-12/IL-18-treated tumours." (PMID 36140243, 2022). "IL18 could exert an inflammation-dependent tumor suppressor effect by promoting tumor-infiltrating T-cell differentiation, activity, and survival." (PMID 36544782, 2022). "In addition to EVs, other factors secreted by CAR-T cells, such as IL-12, IL-15, and IL-18, play roles in killing tumor cells." (PMID 35410257, 2022). "Favorable, anti-inflammatory cytokines, such as IL-1RA, IL-7, and MIP-1β were detected in higher concentrations in responding patients, while pro-inflammatory, tumor-promoting cytokines, such as IL-18 and IL-1β, were higher in patients with early progressive disease." (PMID 36091056, 2022). "cDC1 are the major source of CD8+ T cell chemoattractants CXCL9 and CXCL10; these chemokines drive T cell recruitment and anti-tumor immunity as well as suppress angiogenesis by secretion of anti-angiogenic factor such as IL-12 and IL-18." (PMID 35759090, 2022). "As for IL-1β, IL-18 is an essential inducer of anti-tumor immunity." (PMID 35517498, 2022). "Activation of tumor-specific or bystander CD8+ T cells could be further enhanced by the high levels of cytokines like IL-18, augmenting antigen-independent IFN-γ production and creating a more proinflammatory environment." (PMID 35862190, 2022). "Similar to IL-1β, IL-18 could also promote tumor progression by regulating the myeloid differentiation factor 88 (MyD88)/NF-κB signaling pathway." (PMID 36237303, 2022). "On the one hand, inflammasome, such as IL-18, could induce pyroptosis and inhibit tumor cell proliferation; On the other hand, the cumulative effect of inflammatory bodies could also build a suitable microenvironment for tumor growth." (PMID 35957895, 2022). "One possible reason might be the high-affinity IL18 decoy receptor, which limits anti-tumor activity in preclinical studies." (PMID 36131941, 2022). "Like IL-1β, IL-18 exhibits a dual-role in tumor development by regulating the TIME." (PMID 35739593, 2022). "Furthermore, differential gene expression analysis showed that IL-18 signalling pathway was significantly more enriched in IIH-FH tumours than IIL-FL ones." (PMID 36253523, 2022). "Additionally, regulatory T cell (Treg) tumor infiltration was reduced, which was due to the loss of AIM2-dependent production of IL-1β and IL-18." (PMID 35432377, 2022). "Additionally, IL-18 can induce tumor Hapten by activating natural killer (NK) cells, and NK-mediated cytotoxicity of tumor cells, which exert an important role in immune response." (PMID 35865545, 2022). "IL-18 could also enhance the differentiation of Th1 cells and facilitate the priming of effector cells including helper NK cells into tumor site." (PMID 35529882, 2022). "The results of co-culture and antibody neutralization experiments suggested that macrophage-derived IL-18 may be a key cytokine in the resveratrol anti-tumor effect of CD8T cell activation." (PMID 36339614, 2022). "It was reported that IL-18 can also mediate evasion of anti-tumor immune response." (PMID 36237303, 2022). "The inflammasome-dependent cytokines IL-18 and IL-1β play a central role in anti-tumor immunity." (PMID 35517498, 2022). "A recent in vivo study showed that macrophage-derived IL-18 inhibits tumor blood vessel formation." (PMID 35626056, 2022). "IL-6 was highly expressed in the tumor microenvironment; it could enhance the secretion of IL-1β and IL-18 and trigger the inflammatory storm in vivo." (PMID 35464414, 2022). "IL-18 also exerts a dual function of promoting or suppressing tumor progression." (PMID 36237303, 2022). "IL-18BP-based therapy may be a potential therapeutic modality for clinical scenarios where IL-18 can promote tumor growth." (PMID 35529882, 2022).
tumor (continued). "A previous study reported that tumour‐derived IL18 could induce PD‐1 expression on NK cells, which resulted in a poor prognosis in patients with TNBC." (PMID 35233921, 2022). "In addition, IL-18 is upregulated in tumor-infiltrating lymphocytes (TILs) secreted by inflammasomes." (PMID 36605437, 2022). "An engineered decoy-resistant IL-18 restored IL-18 signaling and subsequent anti-tumor activity." (PMID 36032110, 2022). "The RdB/IL-12/IL-18 therapy improved anti-tumour effects, as well as increased survival." (PMID 36140243, 2022). "IL-18 impairs NK and T cell function, which in turn impairs recognition of tumor antigens." (PMID 36497316, 2022). "On the other hand, IL-18 can induce angiogenesis, which helps tumor metastasis and proliferation." (PMID 36675746, 2022). "Treatment with a combination of IL-18/IL-12 decreased tumor burden in mice with established HCC." (PMID 36313762, 2022). "The potential mechanism may be that IL-18 plays an important role in anti-tumor immunity through enhancing interferon-γ production and Fas ligand dependent cytotoxicity of immune cells, and the dose of IL-18 was correlated with the level of serum IFN-γ." (PMID 35865545, 2022). "Overall, data to date point to IL1R8 as a new negative regulator of IL-18 signaling in NK cells that could be targeted to unleash NK cell activity, with expected enhanced benefits if IL-18 is expressed within the tumor microenvironment." (PMID 34503073, 2021). "It is still unknown whether tumor cells from CRC possess a functional caspase-1/IL-18 axis that could modulate the Th1/Tc1 response." (PMID 33430344, 2021). "Similarly, the levels of IL-8 and IL-18 in serum have been shown to be useful markers of tumor invasiveness in HCC patients." (PMID 34948424, 2021). "Therefore, we investigated the anti-tumor effect of the CTXpre/ACT/CD4post-induced milieu in the long-term by blocking the IL-18 signal, which played a crucial role in the function of IL-18Rαhi CD8+ T cells in vitro and in vivo." (PMID 34493727, 2021). "Downstream of inflammasome and GSDMD activation, IL-1β and IL-18 can also have a beneficial effect as they play a pivotal role in the activation of dendritic and natural killer (NK) cells, respectively, and can, thereby, promote anti-tumor immune responses." (PMID 34490126, 2021). "In addition, IL-18 potentiates antitumor immunity in the tumor microenvironment via the innate and adaptive immune responses." (PMID 33507690, 2021). "The downregulated IL-18 levels may indicate the reduced activity of the inflammasome, which may contribute to both the tumor sensitivity and the modest inflammatory responses in K8flox/flox; Villin-Cre mice." (PMID 34951664, 2021). "Notably, the response was augmented by the addition of IL-18, suggesting the crucial role of IL-18 signaling in the anti-tumor activity of this subset." (PMID 34493727, 2021). "Indeed, the level of IL-18 secreted was significantly higher in CRCs with aCasp1+ tumor cells than in those with aCasp1− tumor cells." (PMID 33430344, 2021). "IL-1β and IL-18 can promote carcinogenesis and tumor progression by inducing inflammation." (PMID 34104103, 2021). "We identified three expression patterns of IL-18 in tumor cells." (PMID 33430344, 2021). "Interestingly, NLRP3 is required for the suppression of CRC metastatic growth in the liver, and its tumor-suppressive function is mediated by IL-18 production, which acts on NK cells." (PMID 34064909, 2021). "In this scenario, IL-18-driven emergence of PD-L1hi NK cells might be part of the tumor-promoting effects of this cytokine." (PMID 34616407, 2021). "Interleukin (IL)-18, a member of the IL-1 family, activates the immune cells involved in both innate and adaptive immune responses, thus increasing the immune defense against tumor cells." (PMID 33507690, 2021).
tumor (continued). "Similar to IL-1β, upregulation of IL-18 may facilitate tumour immune escape by recruiting MDSCs and promoting metastatic ability in tumour cells via upregulation of the vascular endothelial growth factor (VEGF)." (PMID 33918087, 2021). "The upregulation of tumour-derived IL-18 may drive the massive infiltration of leucocytes but fail to halt the tumour growth." (PMID 33918087, 2021). "In addition, patients in the low-risk group had a higher expression level of cytokines in the tumor tissues, such as IL-2, IL-6, and IL-18, which was consistent with more infiltrating immune cells in the low-risk group." (PMID 34616734, 2021). "In this model, epithelial cell-derived IL-18 reduction and immune system homeostasis weakening in the colon could be the explanation for promoting tumor progression." (PMID 33658393, 2021). "Indeed, tumor-derived IL-18 has been found to promote tumor progression, despite its pro-inflammatory function." (PMID 33718235, 2021). "The next step was to assess whether tumor cells possessed the enzymatic machinery essential for the cleavage of pro-IL-18 into its mature form, i.e., active caspase-1, which is tightly regulated by the inflammasomes (NLRP or NLRC)." (PMID 33430344, 2021). "A loss of IL-18 could decrease the ability of effector cells to secrete IFN-γ and promote tumor cell survival." (PMID 33290281, 2021). "However, IL-18 has been reported to have both anti-cancer and pro-cancer properties, depending on the organ studied and on the tumor environment." (PMID 33430344, 2021). "Indeed, studies from an ESCC animal model revealed that IL-18 deficiency can down-regulate local NK cell anti-tumor immunity by decreasing their IFN-γ production, suggesting that exogenous IL-18 supplementation has potential to delay EC development." (PMID 33995371, 2021). "This was also accompanied by diminished levels of IL-1 and IL-18 at the tumor area." (PMID 34571825, 2021). "We hypothesized that addition of IL-18, which can induce the proliferation of several immune effector cells through inducing IFNγ could synergize with IL-27 to enhance tumor growth control." (PMID 34209203, 2021). "Thus, our findings show that the majority of CRC exhibits an activated functional caspase-1/IL-18 axis in tumor cells, and that IL-18 is able to modulate the IFNγ response of TILs in vitro." (PMID 33430344, 2021). "We utilized RNA sequencing (RNAseq) to examine pathways and potential modes of action in tumors, finding many common yet some unique pathways and immune effectors that 27pepL might utilize alone, or in combination with IL-18, to halt tumor growth." (PMID 34209203, 2021). "Finally, mutant KRAS silencing led to increased expression of MHC I surface proteins on tumor cells and production of IL-18, inducing ultimately tumor regression." (PMID 33494181, 2021). "The “heterogeneous low” pattern included CRC with an IL-18 staining intensity lower in tumor cells than in the paired normal epithelial cells (10/192 = 5%) and CRC with an IL-18 staining intensity equal to that of paired normal epithelial cells in 10–49% of tumor cells (43/192 = 22%)." (PMID 33430344, 2021). "Notably, CTXpre/CD4post-exposed ex-T and en-T cells heightened the frequency of IL-18Rαhi subset, which was highly polyfunctional and exhibited TCR/IL-18 signal-dependent anti-tumor activity in vivo." (PMID 34493727, 2021). "Although this specific combination of cytokines has not yet been used in combination with OV therapies, an oncolytic adenovirus co-expressing IL-12 and IL-18 showed enhanced anti-tumour effects in a murine melanoma model compared to expression of either cytokine alone." (PMID 34888493, 2021). "IL-18 may play an anti-tumor immune role by increasing the activity of CD8+T cells and natural killer cells and promoting IFN-γ anti-tumor activity." (PMID 34805183, 2021). "In the atopic dermatitis mouse model, the knockout of IL-18 reduces skin lesion formation." (PMID 34840991, 2021).
tumor (continued). "In order to assess whether pro-IL-18 expressed by tumor cells can be processed and secreted as a mature form, we first assessed the expression of active caspase-1, essential for the processing of IL-18." (PMID 33430344, 2021). "An increased level of serum interleukin 18 (IL18) was found in patients with BC, which might be the result of the patients’ immune systems fighting to inhibit the growth of tumor cells." (PMID 34266411, 2021). "While NK cells positively promote DC infiltration and maturation via release of pro-inflammatory cytokines such as interferon (IFN)-γ, myeloid-derived cytokines, including interleukin (IL)-12, IL-15, and IL-18, critically promote NK cell maturation, proliferation, and anti-tumor functions." (PMID 33584718, 2020). "Similarly, the subsequent transwell assay indicated that silencing IL‐18 reversed the tumour‐promoting effect of Pin1 in cell migration and invasion." (PMID 32347623, 2020). "Similarly, ASC deletion or IL-18 blockade in tumor cells increased apoptosis, and in tumor samples elevated levels of IL-18 and ASC mRNA showed positive correlation, supporting a role for IL-18 in protecting tumor cells from apoptosis." (PMID 32117971, 2020). "For caspase-1 and IL18, the pattern of stained cells was similar in hen and human tumor tissue." (PMID 31923221, 2020). "TLR2 agonist treatment to recruit NK cells, combined with additional components that activate NK cells (e.g. type I IFNs or IL‐12 and IL‐18), could potentiate NK cell‐mediated tumor clearance." (PMID 32696994, 2020). "In addition, they showed that combinatorial therapy made wide-ranging tumor suppression and survival rate in a large number of mice, whereas no survival was detected in mice treated with doxorubicin or IL-18 alone." (PMID 32340275, 2020). "However, IL‐18 is overexpressed in tumour tissues and its expression correlates with tumour progression, metastasis and poor prognosis in some cancers, such as PDAC, extranodal natural killer/T‐cell lymphoma and renal cell carcinoma." (PMID 32347623, 2020). "Furthermore, it has been revealed that IL-18 derives CAR-T cells’ polarization into T-bet high FoxO1 low effector cells that trigger an acute inflammatory response against tumor cells." (PMID 33167514, 2020). "This may be explained by the capacity of IL-18 within the tumor to turn “cold” resistant tumors (high macrophages) into “hot” tumors (high CD8+/IFNγ+/PD-1+ T cells)." (PMID 33261061, 2020). "Given an established role for IL-18 and IL-27 in stimulating optimal IFNγ production and Th1 responses, our data suggest that increased tumor burden in the mice receiving AdIL-17A-transduced 4T1 cells could be due to the progressive loss of Th1 immunity." (PMID 32770025, 2020). "IL‐18 impairs NK and T cell function, thus impairing host immune responses to tumor antigens." (PMID 32419290, 2020). "Though IL‐18 could enhance tumour immunity to some extent, our research found that IL‐18 protein was elevated in tumour tissues and that IL‐18 mRNA expression was a predictor of poor prognoses." (PMID 32347623, 2020). "This comparative study demonstrates for the first time that TCR bypass stimulation i.e., γδ T cells stimulated solely with combined IL-2/IL-12/IL-18 is enough to induce γδ T cells that exhibit the same efficiency in anti-tumor activity as their counterparts after TCR crosslinking." (PMID 31947966, 2020). "IL-18 staining was predominantly localized in the cytoplasm of colonic epithelial and tumor cells." (PMID 33294056, 2020). "Activation could occur through direct recognition of microbial, or potentially tumor, antigens, but IL-12/IL-18 can also mediate TCR-independent activation of MAIT cells." (PMID 32508830, 2020). "Taken together, these studies highlight the fact that IL-18 may improve immunotherapy only in some cases, and that it depends on the tumor immune-infiltrating cells and their capacity to secrete inhibitory molecules, such as IL-18BP." (PMID 33261061, 2020).